APC (APC regulator of Wnt signaling pathway)
Diseases named in the same sentence as APC in open-access papers (continued):
Sharing a sentence is not in itself a finding about the gene and the disease.
adenoma (continued). "It has been well established that the inactivation of APC is the major pathway for adenoma formation." (PMID 36859772, 2023). "In another study analyzing the role of claudin-1 in adenoma formation in adenomatous polyposis coli (APC) in mice, APC-Cldn1 mice showed significantly increased colonic tumor growth, size, and decreased survival." (PMID 37627123, 2023). "At the core of the classical pathway of CRC development (‘adenoma–carcinoma sequence’) are genetic alterations of several suppressor genes such as APC, responsible for the development of FAP, and a gene known as colorectal mutant cancer protein (MCC)." (PMID 37760539, 2023). "In CRC involving the APC/β-catenin pathway, cyclooxygenase-2 (COX-2) is often implicated in the early and later stages of the adenoma sequence, driving the formation into a carcinoma." (PMID 36765950, 2023). "Most biomarkers for the outcome of adenocarcinoma used in histology are related to the adenoma-carcinoma pathway and show mutations in oncogenes such as KRAS, NRAS, BRAF, APC, and DDF." (PMID 38187473, 2023). "MSH3-associated CRC seems to follow the classic APC pathway, as patients with adenomas and CRC carrying APC mutations showed MSH3 deficiency, as confirmed in this study." (PMID 37835512, 2023). "Mutational analysis showed a 2-bp deletion mutation at codon 443, which generates a premature stop codon at codon 461 of the APC gene, and Western blot analysis demonstrated both wild-type and truncated APC proteins in adenoma tissue." (PMID 36826061, 2023). "Consistent with findings in mice, multilineage differentiation capacities were restored upon Sox9 knockdown in adenoma organoids derived from APC-mutant human colonic tissues." (PMID 37894295, 2023). "The model allows for the calculation of the probabilities to develop an advanced adenoma through the APC-/- and KRAS pathways, functions PAPC(t) and PKRAS(t)." (PMID 35416770, 2022). "APC gene typically acts as a driver gene in adenoma-to-carcinoma sequence through aberrant Wnt signaling." (PMID 35402217, 2022). "These mice harbor a mutation closely mirroring APC protein truncations in human CRC, resulting in the generation of adenomas which recapitulate early events in human CRC that follows the adenoma-adenocarcinoma sequence." (PMID 35658010, 2022). "We analyzed 20 genes related to gastric tumors and polyps through next-generation gene sequencing (NGS) and found APC and KRAS gene mutations in the adenoma tissue." (PMID 35508985, 2022). "Mutations in the adenomatous polyposis coli (APC) tumor suppressor gene cause the intracellular accumulation of β-catenin, which activates the transcription factor TCF-4 and leads to adenoma formation, a precursor lesion of colon cancer." (PMID 36077707, 2022).
adenoma (continued). "While the first step in both is the loss of APC function, in the CIN pathways it is usually the sole mutation, which leads to the formation of early adenoma." (PMID 35884974, 2022). "Multiple somatic inactivating mutations in the APC and KRAS genes have also been found in a study on 37 FAP-derived adenomas." (PMID 33923068, 2021). "In line with previous studies, the authors showed that somatic inactivation of the APC gene constitutes the most frequent event in adenomas from FAP patients and that the derangements of Wnt signaling represented the most affected pathway." (PMID 33923068, 2021). "In the first pathway, adenoma formation occurs in an MMR-proficient background, and carcinogenesis is characterized by APC and/or KRAS mutation and IGF2, NEUROG1, CDK2A, and/or CRABP1 hypermethylation." (PMID 34201893, 2021). "Noteworthy, RNF43 and APC mutations, which both lead to WNT pathway activation and are usually mutually exclusive, often co-exist in LS patients, both in adenomas and adenocarcinomas." (PMID 34201893, 2021). "It was previously shown that APC deficiency was associated with an increase in EGFR activity and c-Src expression in ApcMin/+ mouse adenomas and intestinal enterocytes." (PMID 34926717, 2021). "The authors also showed an early development of intra-tumor heterogeneity (ITH) since most adenomas harbored sub-clones arising from an APC-mutant founder clone." (PMID 33923068, 2021). "For example, it is know that CDK4 activation in CDK4R24C/R24CApc+/min mice leads to significant increased in tumor vascularity in comparison to CDK4+/+Apc+/min mice or APC+/min mice, while knocking out CDK4 in APC+/min mice reduces adenoma development." (PMID 35002699, 2021). "As we had performed sequencing of APC in the adenomas of another patient with MSH3-related adenomatous polyposis (sister of 1661.2) in a previous study, the eight APC variants found in those adenomas were also considered in these analyses." (PMID 34843512, 2021). "ALDH1+ cells are found at low levels at crypt bases, but increase during progression from normal to APC-mutant adenoma." (PMID 33562604, 2021). "This suggests that CtBP2 is also crucial for stemness in APC deleted cell of adenomas from FAP patients, at least in vitro." (PMID 33972635, 2021). "The results of RCT showed that, in normal appearing colorectal mucosa of individuals with a history of adenoma, the expression of APC (adenomatous polyposis coli) and β-catenin is modified by calcium supplementation." (PMID 34122548, 2021). "Ahadova and colleagues found that somatic mutations in APC and KRAS genes were mainly associated with MMR-D adenomas in LS patients." (PMID 33923068, 2021). "Deletion of APC leads to adenoma formation in the mouse small intestine due to hyperactivation of the Wnt pathway." (PMID 32335811, 2020). "Activation of Wnt signaling in the progression of this kind of adenoma to carcinoma is less clear and in the past individuals with SPS were tested for APC and MUTYH mutations, founding some missense APC mutations in patients with serrated pathway neoplasia." (PMID 32258104, 2020). "Mutation of the adenomatous polyposis coli (APC) gene and the CTNNB1 gene encoding β-catenin is an initial event driving to the development of adenoma in most sporadic cases." (PMID 32962187, 2020).
adenoma (continued). "APC promoter hypermethylation is an early event in the classical adenoma-carcinoma sequence of the colon." (PMID 32678024, 2020). "APC was the most commonly mutated gene, identified in 77% of the MSS cases, in line with its known role as the adenoma-initiating mutation in CRC." (PMID 32895052, 2020). "Initiating APC and BRAF mutations were usually public (shared between matched adenoma and carcinoma)." (PMID 32895052, 2020). "The APC mutant mice developed many adenomas in their small intestines and a few in the large intestine that rarely progress to invasive adenocarcinoma." (PMID 31766149, 2019). "Hung and coworkers developed a stochastic somatic mutation model of intestinal carcinogenesis based on the loss of APC and KRASG12D/+ mutation; this model showed the progressive tumor development and the progression from adenoma to carcinoma." (PMID 29652830, 2018). "Immunohistochemical analysis of adenomas from CDX2;APC mice showed that these lesions were highly proliferative, as characterized by Histone H3-positive cells, while adenomas from CDX2;APC;PID mice had lower levels of Histone H3-positive cells." (PMID 30150766, 2018). "APC(+/Min) models in rodents show extensive polyposis which almost ubiquitously involves the small bowel, whereas adenoma or adenocarcinoma in human small bowel is a very rare event." (PMID 29462896, 2018). "The tumor-originating cell within the human colon has been identified to be almost always a stem cell with a first hit in the APC gene, and a second hit in this gene is sufficient to induce adenoma formation, a benign precursor of malignant adenocarcinoma." (PMID 30687642, 2018). "Sequencing studies showed that LS-associated MMR-deficient adenomas display a lower frequency of APC or CTNNB1 mutations (37%), compared to that observed in LS-associated MMR-proficient adenomas (72%) or in sporadic adenomas." (PMID 29652830, 2018). "Studies of the progression from normal to mutant APC epithelium to adenoma have found that ALDH1-positive cells increased in number and became distributed farther up the crypt." (PMID 29652830, 2018).
adenoma (continued). "Several mutations and deletions in the APC gene and methylation in its promoter have been described in FAP, and more than two thirds of CRC and adenomas patients have APC gene mutations." (PMID 29050326, 2017). "Our result indicated that the APC promoter is 5.76 times more frequently hypermethylated in adenoma than in normal colorectal tissue." (PMID 28515349, 2017). "For many years it was believed that the right sided typical SSA are driven by CIMP and counteractively to conventional adenomas by CIN, especially due to the APC gene’s frameshift mutation." (PMID 28234922, 2017). "Presence of APC, KRAS, NRAS, and GNAS mutations in HGCA well matched ‘classical adenoma-carcinoma model’." (PMID 28179590, 2017). "To prove functional relevance in vivo, we preliminarily tested the effect of niclosamide on adenoma formation in APC-MIN (multiple intestinal neoplasia, APCΔ850) mice model." (PMID 28418862, 2017). "Another study performed BEAMing PCR to detect mutant APC circulating DNA in patients with adenomas and metastatic and localized CRC and found that CRC had higher mutant APC DNA than controls." (PMID 28088238, 2017). "The frequency of APC promoter hypermethylation was significantly increased in adenoma than in normal colorectal tissues, OR was 5.76, 95%CI, 2.45-13.56; p<0.0001, I2=0%." (PMID 28515349, 2017). "Over 80 % of adenomas and CRC exhibit APC mutations and a further 5–10 % are showing mutations or epigenetic changes in other WNT signalling components (e.g. β-catenin) that equally result in hyperactivation of the WNT pathway." (PMID 27325016, 2016). "We prepared organoid cultures from APC-mutated normal gut epithelium (MIN) and adenomatous polyps of APCmin/+ mice (adenoma) and analyzed them via RNA-seq." (PMID 27386949, 2016). "Collectively, these data demonstrate that tumor-host cell competition is essential to drive the growth of APC−/− adenomas in the Drosophila adult midgut." (PMID 26853366, 2016). "Allele frequencies of the SNPs were compared for patients with <100 colorectal adenomas versus patients with ≥100 adenomas, using generalized estimating equations with the APC genotype as a covariate." (PMID 26880076, 2016). "The number of adenomatous polyps in the bowel is used to stratify APC-associated polyposis into a classical form (FAP; 100 adenomas or more) and attenuated form (AFAP; below 100 adenomas)." (PMID 27683109, 2016). "A two-step model for colon adenoma initiation is caused by adenomatous polyposis coli (APC) mutation as the first step, whereas KRAS activation and β-catenin nuclear localization promote adenoma progression to adenocarcinoma as a second step." (PMID 27007150, 2016). "This is consistent with the finding that targeted APC deletion in murine LGR5+ colon SC gave rise to adenomas." (PMID 26744320, 2016). "Lineage tracing studies have shown that murine adenomas can originate from crypt base SC origin, since targeted APC deletion in murine LGR5+ intestinal SC gave rise to adenomas." (PMID 26744320, 2016). "APC was progressively downregulated and EphB6 was upregulated as disease progressed toward adenocarcinoma, but both were highly expressed in adenomas." (PMID 27145271, 2016). "Altogether, these data indicate that APC−/− adenomas engage in cell competition with surrounding wild-type cells and, by acting as supercompetitors, cause attrition of the host tissue." (PMID 26853366, 2016).
adenoma (continued). "If a single-gene approach to testing was utilized in this scenario, practitioners would have likely started with the APC or MUTYH gene based on his adenoma history and then moved on to the mismatch repair genes of Lynch syndrome." (PMID 29225998, 2016). "The third is the alternative pathway, which starts from normal mucosa via villous, partly serrated adenomas (with KRAS, BRAF, and APC mutations and CIMP) and results in colon cancer with poor prognosis (with CIMP)." (PMID 26738600, 2016). "β-Catenin promoted a universal capacity for self-renewal and expression of cancer stem cell markers, similar to cultures derived from APC−/− adenoma." (PMID 26425654, 2015). "Oncogenic KRAS has a tumor-promoting role in conventional adenoma initiated by loss of APC, while oncogenic BRAF can initiate another type of CRC precursor, termed serrated adenoma, independently of APC." (PMID 26425654, 2015). "ANOVA analysis identified AXIN2, which plays an important role in Wnt signaling pathway cooperating with APC and b-catenin, being more frequently altered in Group 2 that included the serrated adenomas." (PMID 24964857, 2014). "Mixed effects models revealed that mutations in APC, BRAF and KRAS occur at the transition from normal to adenoma stages whilst the hypermethylation of the Wnt antagonists continued to accumulate during the transitions from adenoma to carcinoma stages." (PMID 25432628, 2014). "Germline mutation of one allele of the adenomatous polyposis coli (APC) gene underlies the vast majority of FAP cases, with adenomas arising in large part from the somatic inactivation of the remaining wild type copy of the APC gene." (PMID 24763434, 2014). "We first analyzed β-catenin expression in adenomas of APC+/min mice and observed increased expression levels and nuclear accumulation of β-catenin regardless of the intestinal SIRT1 deletion." (PMID 23799088, 2013). "Among these genetic alterations, inactivation of the APC gene was often detected in small adenomas, the early stage of CRC development." (PMID 23301059, 2013). "We observed a marked decrease in apoptosis rate in high-grade adenomas from CDON−/−APC+/1638N mice compared to that in size-matched CDON+/+APC+/1638N controls." (PMID 23940460, 2013). "Several studies have shown that APC inactivation in vivo in mice is sufficient to initiate adenoma development." (PMID 22509309, 2012). "The APC gene is thought to be the initial event transforming a normal cell into an adenoma, and is found in ~80% of all colorectal carcinomas." (PMID 22272141, 2011). "Responses of Smad4-reexpressing cancer cells were compared to responses of LT97 cells, a cell line derived from a late adenoma and carrying inactivated APC as well as an activated Ki-ras oncogene." (PMID 20307265, 2010). "Deletions in APC were detected in six cases (one serrated lesion and five adenomas); insertions in five adenomas." (PMID 24212608, 2010). "In accordance with this model, adenomas and even single aberrant crypt foci, the earliest putative CRC precursors, were shown to harbour mutations in the APC gene." (PMID 24212608, 2010). "Four samples (one serrated lesion and three adenomas) showed alterations both in APC and in B-Raf and three samples (two serrated lesions and one adenoma) in K-Ras as well as in B-Raf." (PMID 24212608, 2010). "In this study, we found notably augmented levels of total APC mRNA levels (from promoters 1A and 1B) as well as APC 1B mRNA in the adenomas investigated by qRT-PCR, of which 13 out of 16 samples displayed APC promoter 1A hypermethylation." (PMID 20208994, 2010). "Adenomas start to grow in the colorectum of patients with FAP when a cell acquires a somatic "second hit" at the APC locus, leading to loss of critical APC functions." (PMID 19515250, 2009).